PINK1 (PTEN induced kinase 1)
Diseases named in the same sentence as PINK1 in open-access papers (continued):
Sharing a sentence is not in itself a finding about the gene and the disease.
tumor (continued). "This suggests that PINK1 may play multifaceted roles in tumor biology beyond its role in mitochondrial functions." (PMID 39472438, 2024). "Upregulation of STMOL2 induces mitophagy and tumor metastasis via interaction with PINK1 in HCC." (PMID 36831455, 2023). "Furthermore, they also highlighted that PINK1 disruption simultaneously increased xenografted tumor growth." (PMID 37047483, 2023). "Parkin and PINK1 deletions synergistically promote tumor development." (PMID 37833780, 2023). "Therefore, the expression of Il6, Nos2, Ccl2, Spp1, Tnf, Acat2, Aox1, Crem, Gls2, Per3, Pink1, Txnip, and Ypel3 was examined in acidosis upon simultaneous transfection with microRNA mimics or antagomirs in two tumor lines in vitro and in vivo." (PMID 38069241, 2023). "Therefore, suppression of Atad3a reduces tumor progression by facilitating antitumor immune responses, and the effect was dependent on Pink1, indicating a crucial role of the Atad3a-Pink1 mitophagy axis in the regulation of tumor immune microenvironment." (PMID 36627348, 2023). "Abnormal PINK1 expression promotes tumor cell proliferation and invasion indefinitely." (PMID 37833780, 2023). "PINK1 promotes tumor cell invasion and migration depending on its kinase activity." (PMID 37940999, 2023). "In both Gpr176−CKO mice model and the subcutaneous tumor model, loss of GPR176 significantly diminished BNIP3L phosphorylation, while a slight alteration in PINK1 phosphorylation level was observed, suggesting that GPR176 mainly modulated BNIP3L phosphorylation both in vitro and in vivo." (PMID 36905238, 2023). "Lower levels of PINK1 expression in HCC tumor tissues than in adjacent tumor parts indicate that mitophagy could be blocked in highly proliferative cells." (PMID 38003445, 2023). "In tumor tissues, all samples were positive for PINK1 but with high variability." (PMID 37047483, 2023). "Moreover, GPD1L prevented tumour growth and promoted mitophagy by activating the PINK1/Parkin pathway in vivo." (PMID 37382962, 2023). "Understanding the role of various components such as Pink1/Parkin, BNIP3, FUN14 domain-containing protein 1 (FUNDC1), optineurin (OPTN), microtubule-associated protein 1A/1B-light chain 3 (LC3), etc. in mitophagy will help in managing tumor progression." (PMID 36365094, 2022). "We also show that PINK1 deletion compromised the ability of the Drp1 inhibitor Mdivi-1 to reduce the growth of Ras-transduced cells, supporting that PINK1 acts at least in part by regulating Drp1 to inhibit tumor growth, likely via PINK1-mediated phosphorylation of Drp1." (PMID 35600352, 2022). "PINK1 is a potential tumor suppressor in GBM, and its overexpression may form a therapeutic strategy for inhibiting growth of GBM cells." (PMID 36552827, 2022). "PINK1 knockdown or regorafenib treatment alone significantly delayed tumor growth." (PMID 35370635, 2022). "This suggests that PINK1 may support mutant Ras-mediated tumorigenesis by stimulating fission to facilitate tumor growth." (PMID 35600352, 2022). "This is the case of PTEN-induced kinase 1 (PINK1), which may either be oncogenic or suppress tumor growth; similarly, the protein parkin modulates tumor growth." (PMID 35409135, 2022). "Moreover, the average volume of tumor xenografts with shPINK1 was smaller than that with shNTC, further suggesting that PINK1-mediated mitophagy alleviates sorafenib- or regorafenib-induced antitumor effects." (PMID 35370635, 2022). "Recent studies have suggested that PINK1 could directly regulate pathways that are important in DNA mismatch repair, drug resistance, and tumor progression." (PMID 32154065, 2020).
tumor (continued). "Similarly, inhibition of PINK1/Parkin-mediated mitophagy was regarded as an anti-tumor mechanism of several Chinese herb extracts (for example matrine and alantolactone) due to the promotion of apoptosis in HepG2 cells." (PMID 32244304, 2020). "Therefore, the inhibition of PINK1-PRKN–mediated mitophagy restores the radiosensitivity of tumor cells." (PMID 33262988, 2020). "In addition, in a KRAS-driven tumor model, the depletion of PINK1 or PRKN promotes pancreatic tumorigenesis in mice." (PMID 33262988, 2020). "There have been several studies about the role of PINK1 expression in tumor immune function." (PMID 33244455, 2020). "Furthermore, the roles of PINK1 in neuroscience have been established and our study revealed the tumor-suppressive roles of PINK1 in HCC." (PMID 31819034, 2019). "Additionally, the drug combination upregulated PINK1, IRF1, PPP1R15A, CRABP2, SCRN1, LIMA1, and TGFBI; all genes associated with tumor suppression functions in PCa." (PMID 29545934, 2018). "PINK1/Parkin-dependent mitophagy was discovered thanks to an artificial system based on the overproduction of a fluorescently tagged Parkin protein in a tumor-derived cell line devoid of Parkin, and the use of the protonophore CCCP to depolarize the whole mitochondrial network." (PMID 28507507, 2017). "Pink1 was first identified as a PTEN-inducible kinase in Pten mutant tumour cells transfected with a Pten expression construct, leading us to hypothesise that the effects of Pten5 might be mediated by modulation of Pink1 levels." (PMID 26599788, 2015). "Thus, PINK1 may act either as a tumor suppressor by maintaining mitochondrial integrity or as a promoter of tumorigenesis through metabolic reprogramming and apoptosis resistance." (PMID 40243539, 2025). "However, much current evidence about PINK1 addresses a duality of its function and may stem from its role in regulating mitophagy, which may be tumor-promoting in some circumstances and tumor suppressive in others, depending on the cellular context." (PMID 37047483, 2023). "Furthermore, PINK1 and Parkin have been proposed as tumor suppressor factors." (PMID 38155968, 2023). "Therefore, the results are consistent with other results published in the literature, where it has been shown that PINK1 may play a dual role in tumor progression." (PMID 36830954, 2023). "PINK1 and PARK2 are risk factors for ESCC patients and may be tumor suppressors." (PMID 37833780, 2023). "Reduced levels of phospho-Drp1 (Ser616) in PINK1-/- tumor cells shown here, and impaired PINK1/Parkin-mediated proteasomal degradation of mitofusin, may have contributed to increased mitochondrial fusion in PINK1-/- tumor cells." (PMID 35600352, 2022). "In contrast, expression of the cell proliferation marker Ki67 in PINK1-/- tumors was reduced compared to WT, while expression of Ki67 in PINK1-/-plus huPINK1 tumors that over-expressed huPINK1 was increased, indicating reversible inhibition of tumor cell proliferation in vivo by ablation of PINK1." (PMID 35600352, 2022). "Therefore, PINK1/Parkin appears to be a novel candidate as tumor suppressor." (PMID 35448958, 2022). "Thus, our observations indicate the tumor-suppressing role of PINK1." (PMID 33888730, 2021). "In addition, PINK1 is considered to be a positive regulator of the cell cycle, and thus may induce tumor development." (PMID 30344951, 2018). "Mutation analysis also showed frequent alterations in PRKN (34%), OPTN (21%), PINK1 (28%), and SRC (15%), with implications for the tumor microenvironment." (PMID 39859167, 2025). "Similar to our previous results, it also demonstrated a significant elevation in PINK1 and PARKIN expression in tumor tissues subjected to DUSP6 knockdown." (PMID 40936711, 2025). "For example, several studies have shown that activation of the PINK1/Parkin pathway supports mitochondrial quality control in CD8+ T cells and enhances their ability to kill tumor cells." (PMID 41551160, 2025).
tumor (continued). "RN0D is identified as an activator of the PTEN-induced kinase 1 (PINK1)/Parkin pathway, ultimately activating cytotoxic mitophagy in tumor cells." (PMID 40134432, 2025). "Then, we performed IHC staining to analyze PINK1 and PARKIN expression in xenograft tumor sample from nude mice." (PMID 40936711, 2025). "Collectively, these results demonstrated that AC484 exerted anti‐tumor effects by modulating TFRC expression, which in turn disrupted PINK1‐PRKN‐dependent mitophagy." (PMID 40734623, 2025). "We have demonstrated that PTPN2 promotes mitochondrial renewal through PINK1‐PRKN‐dependent mitophagy by suppressing TFRC expression, thereby exerting tumor‐promoting effects in ALK+ ALCL." (PMID 40734623, 2025). "Among them, TAZ was up-regulated in tumor tissue compared with para-cancerous tissue, and the expression of the remaining eight genes (including SLC25A4, SLC25A5, PARK, PINK1, MFN2, HUWE1, VPS13D, and LRBA) was down-regulated in tumor tissue." (PMID 38373978, 2024). "RT-qPCR and Western blot analyses revealed that, compared to the sh-NC group, the sh-SIRT1 group had significantly lower expressions of BNIP3, PINK1, and PRKN and their corresponding proteins in the tumor tissues." (PMID 39266959, 2024). "We assessed the expression of PINK1.AS, OIP5.AS1, HID.AS1, and MAPT.AS1 in tumor pairs using qRT-PCR, which revealed a marked increase in the expression of these chrlncRNAs in tumor tissues compared to adjacent tissues." (PMID 38326441, 2024). "Also, the subsequent activation of an Nrf2/PINK1 (PTEN-induced kinase 1) pathway following a sudden increase in ROS after incomplete radiofrequency thermal ablation (RFA) resulted in a pro-survival effect in tumor cells in vitro, explaining a potential mechanism of HCC resistance after RFA." (PMID 38397806, 2024). "To further elucidate the molecular mechanism underlying the effect of ailanthone against HCC in vivo, we performed IHC analysis to investigate the protein expression of LC3, PINK1, PRKN, BAX, and BAK1 in tumour tissues." (PMID 39723259, 2024). "Taken together, our findings demonstrate that PINK1 regulates the tumor suppressor function of PTEN through its phosphorylation, resulting in promoting tumor metastasis and chemotherapy resistance." (PMID 37940999, 2023). "Additionally, we reveal that ATAD3A, a negative regulator of PINK1-dependent mitophagy, prevents PD-L1 distribution at mitochondria and degradation, thus providing new insight into mitochondria-mediated PD-L1 protein homeostasis regulation in tumor immune microenvironment." (PMID 36627348, 2023). "Sorafenib significantly upregulated the protein levels of PINK1 and PRKN in tumor tissues, while OA strongly reduced these levels." (PMID 37670307, 2023). "PINK1 overexpression can significantly reduce acetyl coenzyme A production in CRC through the HIF-1α-PDHK1-PDHE1α axis, thereby inhibiting tumor growth." (PMID 37881499, 2023). "Collectively, our data indicate that PINK1 phosphorylates PTEN at Ser179, leading to activation of AKT and promotion of tumor metastasis and cell survival." (PMID 37940999, 2023). "In HepG2-derived xenograft model and a PDX model of HCC, CDK9 inhibitor, PHA767491 and oroxylin A (OA) from Scutellaria baicalensis significantly decreased the protein expression of CDK9, PINK1, PRKN, p-SIRT1, FOXO3 and BNIP3 in tumor tissues." (PMID 37670307, 2023). "The result shows that patients with ESCC who had reduced PINK1, PARK2, and tumor size had worse prognoses." (PMID 37833780, 2023). "The in vivo study in the A549-xenograft mice model showed that the anti-tumor effect of elaiophylin was accompanied by the decreased expressions of SIRT1, Nrf2, Parkin, and PINK1." (PMID 36497294, 2022). "PINK1, Parkin, BNIP3, NIX, and FUNDC1 have been reported to facilitate tumor progression and recurrence." (PMID 36207761, 2022). "We further discovered that TPP-SS-ATS-LS inhibited tumor cells proliferation through mitophagy by regulating PHB2 and PINK1 expression." (PMID 35964052, 2022).
tumor (continued). "Several studies have revealed that PINK1, Parkin, BNIP3, and NIX, the most important mitophagy receptors on the OMM, are tumor suppressor genes involved in promoting apoptosis, implying the positive correlation between mitophagy and apoptosis." (PMID 35581181, 2022). "In that study, the authors showed that PINK1 is negatively regulated by MYC, resulting in its suppression in tumor tissues." (PMID 33888730, 2021). "Identical to what have been found, the expression of PINK1, Parkin, and LC3B II in HCC tissues was much higher than that in peri-tumor liver tissues, and the statistical results showed positive correlation between STOML2 and PINK1." (PMID 33446239, 2021). "PINK1/PARK2 pathway-mediated mitophagy is essential for clearance of damaged mitochondria and inhibits tumor development." (PMID 34493296, 2021). "The expression level of PINK1 was restricted in human HCC tumor tissues compared to adjacent normal tissue, suggesting aberrant mitophagy activity in highly proliferative tumor tissues." (PMID 32244304, 2020). "PINK1 and PARK2 mRNA expression in the tumor tissue was weakly correlated (Pearson r = 0.19, p = 0.002)." (PMID 33139776, 2020). "Similar to PINK1/PRKN deficiency in PD, while defect in melatonin may be detrimental in the setting of chronic neuroinflammation, downregulating melatonin may be beneficial in activating innate immune response in the context of tumor-mediated immune suppression." (PMID 33520994, 2020). "A major trigger for mitochondrial clearance in tumor cells is mitochondrial membrane depolarization and hypoxia, activating PTEN-induced putative kinase 1 (PINK1)/Parkin pathway or through Bcl-2." (PMID 31889941, 2019). "We observed via Western blot that CMR treatment led to an upregulation of PINK1 and LC3-II in the tumor samples, indicative of mitophagy induction." (PMID 29934599, 2018). "An in vivo study confirmed that polyphyllin I greatly inhibited tumor growth and induced apoptosis in MDA-MB-231 xenografts, and these effects were enhanced by PINK1 knockdown." (PMID 28060722, 2017). "DJ-1 was shown to suppress the function of the tumour suppressor PTEN, a gene shown to induce PINK1 when overexpressed." (PMID 21203498, 2010). "Dysregulation of the PTEN-induced kinase 1 (PINK1)/Parkin pathway may lead to the accumulation of dysfunctional mitochondria, promoting tumor progression." (PMID 41567244, 2026). "Immunohistochemical analysis revealed that PINK1 was expressed in 65% of tumor samples (13 positive and 7 negative), while GPR55 exhibited high expression in 95% of cases (19 positive and 1 negative)." (PMID 40565152, 2025). "In addition, IHC analysis of the tumor tissues confirmed that DARS2 knockdown considerably reduced PINK1 and CDK4 expressions, which were partially restored upon PINK1 overexpression, consistent with our earlier findings." (PMID 39990673, 2025). "The PINK1/Parkin activator enhances treatment sensitivity and reduces tumor growth and metastasis, while the BNIP3/NIX inhibitor promotes cell survival and drug resistance, facilitating tumor progression." (PMID 41551160, 2025). "Consistently, tissue microarray (TMA) analysis of human tumor tissues revealed that UBR4 expression significantly correlated with LUAD progression and with levels of PTEN-induced putative kinase 1 (PINK1), a crucial mediator of mitophagy-mediated mitochondria quality control." (PMID 40531870, 2025).
tumor (continued). "Unlike PINK1, the downstream Parkin has been reported to inhibit tumor angiogenesis through ubiquitination degradation of HIF-1α at lysine 477, and inhibiting JAK2/STAT3/VEGF pathways in osteosarcoma." (PMID 37407961, 2023). "PINK1 and PARK2 could work as tumor suppressors in ESCC and are likely to become new treatment targets for ESCC." (PMID 37833780, 2023). "In patients with ESCC, PINK1 expression was not affected by age, sex, tumor size, location, lymph node metastasis, or metastasis (P > 0.05)." (PMID 37833780, 2023). "In addition, upregulation of STMOL2 induces mitophagy and tumor metastasis by interacting with PINK1 in HCC, and depletion of PINK1 induces mutant Kras-mediated pancreatic tumorigenesis." (PMID 36831455, 2023). "Among the 25 MRGs exhibiting differential expression between the normal and tumor tissues, only MAP1LC3B, PINK1, PARK2, UBB, and UBC were significantly downregulated in the tumor tissues, while expression of the other genes was significantly upregulated in the tumor samples." (PMID 38155968, 2023). "Furthermore, it has been reported that iron transporters, such as SLC25A37 and SLC25A28, may be degraded by PINK1/Parkin‐mediated mitophagy, thus leading to the accumulation of iron in mitochondria, which can trigger a HIF1a‐dependent Warburg effect and inflammasome activation in tumour cells." (PMID 36200262, 2022). "The shift toward increased mitochondrial fusion in PINK1-/- MEF RasG12D-transformed cells may explain the accumulation of these cells in G2/M, as it is observed in tumor cells after Drp1 knockdown." (PMID 35600352, 2022). "This conclusion is corroborated by the observation that PINK1 ablation also reduced the growth of several RasG13D-transformed human HCT116 tumor cell clones – without decreasing Ras protein expression or Ras GTPase activity." (PMID 35600352, 2022). "In addition, polyphyllin I, a natural compound, decreased tumor growth and promoted apoptosis in MDA-MB-231 xenografts, and PINK1 knockdown boosted these effects." (PMID 35326612, 2022). "Further studies on anti-tumor mechanisms have shown that the novel nano-preparation inhibits tumor cell proliferation through the mitochondrial autophagy pathway, which is mediated by down-regulating PHB2 and PINK1 expression." (PMID 35964052, 2022). "Notably, we detected and compared the expression of PINK1, Parkin, and LC3B I/II in HCC tissues and peri-tumor liver tissues." (PMID 33446239, 2021). "BRCA1 expression was higher in cancerous mammary glands than in noncancerous breast epithelial tissues, whereas PINK1 and Parkin expressions were lower in tumor tissues." (PMID 33888730, 2021). "However, similarly to PINK1/PARKIN, BNIP3 can not only serve as a tumor suppressor, but can also exert oncogenic activity." (PMID 32587855, 2020). "For survival analysis, tumor samples were dichotomized into tumors with absent or low PINK1 expression (low) and tumors with moderate to high PINK1 expression (high)." (PMID 33139776, 2020). "In our study, we noticed a significantly lower PINK1 expression in tumor compared to non-neoplastic tissue." (PMID 33139776, 2020). "Importantly, decreased levels of mitophagy-related BNIP3L and PINK1, as well as increased levels of mitochondrial biogenesis related genes PPARGC1A and PPARGC1B were found in the basal-like tumor samples when compared to the Luminal A subtype." (PMID 31231612, 2019). "In the C26-bearing mice, exercise did not change PINK1 levels as compared to sedentary tumor hosts and BNIP3 levels remained comparable to controls." (PMID 30823492, 2019). "Tumor suppressors PTEN and FOX3A have been shown to induce PINK1 and PARKIN50,51." (PMID 31819034, 2019).